GRPR (gastrin releasing peptide receptor)
Description:
Receptor for gastrin-releasing peptide (GRP). Signals via association with G proteins that activate a phosphatidylinositol-calcium second messenger system, resulting in Akt phosphorylation. Contributes to the regulation of food intake. Contributes to the perception of prurient stimuli and transmission of itch signals in the spinal cord that promote scratching behavior, but does not play a role in the perception of pain. Contributes primarily to nonhistaminergic itch sensation. In one study, shown to act in the amygdala as part of an inhibitory network which inhibits memory specifically related to learned fear (By similarity). In another study, shown to contribute to disinhibition of glutamatergic cells in the auditory cortex via signaling on vasoactive intestinal peptide-expressing cells which leads to enhanced auditory fear memories (By similarity). Contributes to the induction of sighing through signaling in the pre-Botzinger complex, a cluster of several thousand neurons in the ventrolateral medulla responsible for inspiration during respiratory activity (By similarity).
Synonyms: BB2; BB2R; BRS2
Tractability: Small molecule: a structure with a bound ligand is known; it belongs to a druggable protein family. Antibody: UniProt places it where antibodies can reach, with high confidence; its Gene Ontology location is reachable by antibodies, with high confidence; UniProt predicts a signal peptide or a membrane-spanning region; the Human Protein Atlas places it where antibodies can reach. PROTAC: a small molecule that binds it is known.
Target class: GRP-related receptor; Short peptide receptor (family A GPCR); Membrane receptor; Family A G protein-coupled receptor; Peptide receptor (family A GPCR)
Gene: Protein-coding gene on chromosome X (16,123,565 to 16,153,518, forward strand). Ensembl gene ENSG00000126010.
Subcellular location: Cell membrane
Subcellular location (Human Protein Atlas): Plasma membrane
Pathways (Reactome):
Signal Transduction: G alpha (q) signalling events; Peptide ligand-binding receptors
Gene Ontology:
Molecular function: G protein-coupled peptide receptor activity; protein binding; neuropeptide receptor activity; G protein-coupled receptor activity; neuropeptide binding
Biological process: G protein-coupled receptor signaling pathway; motor behavior; phospholipase C-activating G protein-coupled receptor signaling pathway; positive regulation of behavioral fear response; positive regulation of respiratory gaseous exchange; social behavior; learning or memory; neuropeptide signaling pathway; psychomotor behavior; response to external biotic stimulus
Cellular component: plasma membrane; membrane
Homologues: Orthologues: chimpanzee GRPR (99% identical), macaque GRPR (99% identical), dog GRPR (94% identical), pig GRPR (93% identical), rabbit GRPR (93% identical), guinea pig GRPR (92% identical), mouse Grpr (90% identical), rat Grpr (90% identical), tropical clawed frog grpr (78% identical), zebrafish grpr (68% identical), Drosophila melanogaster CCHa1-R (35% identical), Drosophila melanogaster CCHa2-R (35% identical). Paralogues in human: NMBR (55% identical), BRS3 (51% identical), EDNRB (29% identical), EDNRA (28% identical), GPR37 (24% identical), NTSR1 (22% identical), NMUR1 (21% identical), GPR37L1 (21% identical), TRHR (20% identical), NMUR2 (20% identical), MLNR (19% identical), GHSR (19% identical), and 3 more.
Diseases named in the same sentence as GRPR in open-access papers:
GRPR is named in the same sentence as 108 diseases in open-access papers, as found by Europe PMC text mining. Sharing a sentence is not in itself a finding about the gene and the disease. The quoted sentences say what the papers report.
prostate carcinoma (159 papers, 2011 to 2025). A carcinoma that arises from epithelial cells of the prostate gland. "GRPR has been shown to be expressed in most human prostate cancers; therefore, diagnostic and therapeutic agents targeting GRPR-overexpressed cancers have been widely investigated." (PMID 40305357, 2025). "Prostate-specificmembrane antigen (PSMA) and gastrin-releasingpeptide receptor (GRPR) have been used for diagnostic molecular imaging/therapyof prostate cancer (PCa)." (PMID 39563828, 2024). "While expression of both PSMA and GRPr is increased in prostate cancer cells, the underlying biological mechanisms responsible for this abnormal behavior are distinct." (PMID 38201600, 2023). "Herein, we present the preclinical characterization of [68Ga]Ga-BQ7812; a PSMA/GRPR-targeting radioligand for the diagnostic PET imaging of prostate cancer." (PMID 36672390, 2023). "GRPR is also associated with the growth of human prostate carcinoma and pancreatic cancer by an autocrine loop with gastrin-releasing peptide (GRP)." (PMID 35744904, 2022). "Clinical, histological, and experimental observations have implicated GRP and GRPR in the pathophysiology of prostate cancer progression." (PMID 21745389, 2011). "Therefore, further validation with a larger sample size is necessary to assess the diagnostic value of GRPR PET imaging in lymph node metastasis of prostate cancer." (PMID 38880858, 2024). "GRPR imaging has found interest in prostate cancer diagnostic and staging." (PMID 35223907, 2022). "Gastrin-releasing peptide (GRP) and its receptor (GRPR) have also been linked to cancerous malignancies and GRPR has been shown to induce the release of IL-8 and vascular growth factor in the case in human prostate cancer cell lines." (PMID 34572888, 2021). "Simultaneous targeting of the prostate-specific membrane antigen (PSMA) and gastrin-releasing peptide receptor (GRPR) could improve the diagnostic accuracy in prostate cancer (PCa)." (PMID 31540122, 2019). "Thus, diagnostic imaging of GRPR expression might be a valuable tool in the early discovery of prostate cancer, confined or already infiltrating in the surrounding tissues, providing more therapeutic options for patients." (PMID 38366299, 2024). "However, the majority of these patients could have GRPR expression (>75% in primary prostate cancer and >85% in lymph node metastases), as GRPR expression is associated with small lesions in low-grade prostate cancer." (PMID 37175001, 2023). "Bombesin has a role as a ligand for the gastrin-releasing peptide receptor (GRPR), a cell surface receptor that is overexpressed on prostate cancer cells." (PMID 41149403, 2025). "For in vitro experiments, we chose the human PC-3 prostate cancer cell line, which has a high expression of GRPR at the level of 4·105 receptors per cell." (PMID 40775579, 2025). "A large area of clinical focus using radiolabeled derivatives of BBN or GRPR-targeting peptides continues to be in the area of prostate cancer (PCa)." (PMID 40430268, 2025). "This imaging method provided insights into thedistinct behaviors of mono- vs bis-substituted peptide conjugatesin live PC-3 prostate cancer cells, known to overexpress GRPR, andin A431 cells, known to overexpress the epidermal growth factor receptor(EGFR)." (PMID 41425801, 2025). "The resulting 68Ga‐labeled heterodimers were next fully characterized in vitro in colon cancer HT29 cells (NTS1+/GRPR−) and in prostate cancer PC3 cells (NTS1+/GRPR+) cells." (PMID 39908060, 2025). "In clinical settings, primary prostate cancer can have GRPR overexpression at early stages of disease, while normal prostate and surrounding tissues do not express this receptor." (PMID 40775579, 2025). "Background/Objectives: The gastrin-releasing peptide receptor (GRPR) shows high-density expression in prostate cancer (PCa), especially in the early stages of the disease." (PMID 41155959, 2025).
prostate carcinoma (continued). "Recently, alternative biological targets have been identified, such as gastrin‐releasing peptide receptor (GRPR), which is overexpressed in several cancers, including prostate cancer, particularly in earlier stages." (PMID 40265741, 2025). "Initially tested in an in vivo GRPr-expressing PC-3 prostate cancer model, the combination progressed to early clinical trials, which showed tolerable safety and uptake in neoplastic lesions." (PMID 40863874, 2025). "GRPR was found overexpressed in 100% of early-stage prostate cancer tissues, around 60% of late-stage prostate cancer tissues, and 83.2% of ER-positive breast cancer tissues." (PMID 40283887, 2025). "This study aims to develop new immunotheranostic TMs using BBN2 peptides for diagnostic imaging using positron emission tomography (PET) and UniCAR T-cell therapy to specifically target GRPR in prostate cancer." (PMID 40141329, 2025). "The gastrin-releasing peptide receptor (GRPR) is overexpressed in the majority of primary prostate cancer lesions, with persistent expression in lymph nodes and bone metastases, making it a legitimate molecular target for diagnostic imaging and staging." (PMID 40138074, 2025). "This is especially of relevance for PSMA-negative prostate cancers with regards to PSMA silent metastasis as targeting GRPR would represent important additional therapy options for these patients." (PMID 40141329, 2025). "Using competitive binding assays on PC-3 (Prostate cancer cell line GRPR+) cells and LNCaP membranes (Prostate cancer cell line PSMA+), this compound showed strong and high binding affinity to their respective targets." (PMID 40869454, 2025). "Prostate cancer cells show elevated levels of GRPR expression, whereas the normal prostate shows only minimal presence of this receptor." (PMID 40430268, 2025). "Lu-TacsBOMB5, Lu-LW01110, Lu-LW01142, and Lu-AMBA inhibited the binding of [125I-Tyr4]Bombesin to GRPR-expressing prostate cancer PC-3 cells in a dose-dependent manner." (PMID 40283887, 2025). "A family of RM26 targeting radiopeptides with flexible hydrophilic polyethelyneglycol (PEG) linkers has been evaluated as GRPR radioligands for prostate cancer imaging." (PMID 40775579, 2025). "In colon cancer, GRPR enhances invasion through the RhoA/ROCK pathway, while in prostate cancer, GRPR overexpression promotes a malignant phenotype via activation of AKT1, PKCε, TYK2, and MST1 pathways." (PMID 39768218, 2024). "Radiolabeled NeoB is a promising gastrin-releasing peptide receptor (GRPR)–targeting radiopharmaceutical for theranostics of GRPR-expressing malignancies, e.g., prostate cancer (PCa)." (PMID 37640941, 2024). "Numerous theranostic radiopharmaceuticals with promising preclinical results for use in the management of prostate cancer have been developed over the years based on GRPR-antagonists." (PMID 38675174, 2024). "Gastrin-releasing peptide receptor (GRPR)-antagonists have served as motifs in the development of theranostic radioligands for prostate cancer." (PMID 38675174, 2024). "Previous research has shown that GRPR is overexpressed in several cancers, including small cell lung cancer, breast cancer, prostate cancer, and pancreatic adenocarcinoma." (PMID 39768218, 2024). "The Ki values of Ga-LW02075, Ga-LW02050, and Ga-SB3 were measured using GRPR-expressing PC-3 prostate cancer cells via a cell-based competition binding assay." (PMID 38999054, 2024). "Previous studies have reported that PET/CT imaging targeting GRPR has a sensitivity of approximately 70% for lymph node metastasis in prostate cancer patients, but previous study only included three patients with a total of ten lymph node metastases." (PMID 38880858, 2024). "The combination of PSMA-PET and GRPR-PET can better classify the lesions in the prostate, Compared with PSMA, GRPR has high sensitivity and specificity in patients with prostate cancer." (PMID 38279185, 2024).
prostate carcinoma (continued). "GRPR is an attractive therapeutic target for GRPR-expressing cancers, such as metastatic castration-resistant prostate cancer, breast, colorectal, cervical, and cutaneous melanoma cancers." (PMID 39327021, 2024). "The resulting USPIO(Cy7.5)-BBN nanoparticles demonstrated high specificity towards GRPr-expressing PC-3 cells, indicating their potential for targeted imaging of aggressive prostate cancer." (PMID 39057854, 2024). "In patients with prostate cancer (PCa), imaging with gastrin-releasing peptide receptor (GRPR) ligands is an alternative to PSMA-targeted tracers, particularly if PSMA expression is low or absent." (PMID 38668903, 2024). "Further studies are warranted to establish the radiotheranostic value of the [111In]In-AU-SAR-M1/[177Lu]Lu-AU-SAR-M1 pair, alone or during NEP-inhibition, in the management of prostate cancer or other GRPR-expressing malignancies." (PMID 38366299, 2024). "Targeting of GRPR by means of peptide radionuclide-carriers has been regarded as a promising approach in the treatment of prostate cancer." (PMID 38366299, 2024). "We have long been engaged in the development of peptide radioligands for cancer theranostics, with a great part of our activities being focused on gastrin-releasing peptide receptor (GRPR)-directed analogs for diagnosis/treatment of human prostate cancer." (PMID 39339259, 2024). "Overexpression of GRPR was found in 63%–100% of primary prostate cancers and more than 50% of lymph node and bone metastases." (PMID 39327021, 2024). "In conclusion, we developed a GRPr-specific bimodal MRI/fluorescence nanoparticle contrast agent for prostate cancer imaging." (PMID 39057854, 2024). "Prostate cancer overexpresses specific receptors, including gastrin-releasing peptide receptor (GRPR), prostate specific membrane antigen (PSMA), and integrins, etc.." (PMID 38195680, 2024). "In this regard, the gastrin-releasing peptide receptor (GRPR), overexpressed in various human cancers, including prostate cancer, represents a valid biomolecular target in nuclear medicine." (PMID 38675174, 2024). "Radioligand therapy targeting GRPR is expected to play an important role in the early prevention and treatment of prostate cancer." (PMID 38880858, 2024). "The gastrin-releasing peptide receptor (GRPR) represents a promising target in prostate cancer radiotheranostics." (PMID 38366299, 2024). "The overexpression of neurotensin subtype 1 receptor (NTS1R) in prostate cancer has also been reported in a number of studies, providing the opportunity for double GRPR/NTS1R-targeting." (PMID 39339259, 2024). "Another protein overexpressed in several neoplastic cells, including early prostate cancer, is the gastrin-releasing peptide receptor (GRPr), which recognizes the bombesin peptide selectively and specifically." (PMID 38334567, 2024). "Due to the limitations of PSMA-targeting, other prostate cancer cell markers, including GRPR, need to be further explored." (PMID 37509170, 2023). "In this study, we have preclinically characterized and evaluated a galium-68 labelled PSMA/GRPR-targeting radiotracer for PET imaging of prostate cancer." (PMID 36672390, 2023). "In this contribution, we report on the detailed physico-chemical characterization of the resulting Pt-containing AuNP-BBN-Pt (Pt = Pt1-Pt3) nanoparticles and describe their preclinical evaluation in the prostate cancer PC3 cell line overexpressing the GRPR." (PMID 36593794, 2023). "The radiolabeled IONs presented in this study carried either one or both pharmacophores, a Glu-CO-Lys ligand, targeting PSMA and a bombesin peptide, targeting GRPr, for dual targeting of prostate cancer." (PMID 39380961, 2023). "The gastrin-releasing peptide receptor (GRPR) is overexpressed in prostate cancer (PCa) and in hormone-driven breast cancer (BCa)." (PMID 36980517, 2023).
prostate carcinoma (continued). "With these signal-enhanced molecular targeted nanobubbles, we demonstrated an in vivo dual-photoacoustic/ultrasound molecular imaging of GRPR in a mouse model of prostate cancer." (PMID 36733960, 2023). "Bombesin is known to bind the gastrin-releasing peptide receptor (GRPr), which is overexpressed in multiple human cancers, including prostate cancer." (PMID 36839652, 2023). "The gastrin-releasing peptide receptor is overexpressed in over 80% of estrogen receptor-positive breast cancers and in up to 100% of primary prostate cancers, particularly in prostate cancers of lower grades and smaller sizes." (PMID 36980517, 2023). "So far, in GRPR-positive malignancies targeting, the biggest amount of research is focused on prostate cancer imaging." (PMID 36834867, 2023). "The bombesin derivative RM2 is a GRPr antagonist with strong binding affinity to prostate cancer (PCa)." (PMID 35864350, 2023). "The gastrin-releasing peptide receptor (GRPr) is highly expressed in prostate cancer and other cancer cells, and [177Lu]Lu-labeled GRPr-ligands have demonstrated good tumor uptake and retention, with minimal uptake in healthy tissues." (PMID 38201600, 2023). "Although GRPr is overexpressed in the early stages of prostate cancer, our results indicate that in more advanced stages, such as mCRPC, the expression is lower than PSMA." (PMID 38201600, 2023). "Gastrin-releasing peptide receptor (GRPr) proteins are highly overexpressed in multiple human tumors and have been detected in 63–100% of human prostate cancer tissue." (PMID 35864350, 2023). "Similar to PSMA, GRPr is a membrane-bound tumor biomarker, which is found to be overexpressed in 84% of prostate cancer cells." (PMID 38201600, 2023). "For example, the Chen group designed and evaluated gastrin-releasing peptide receptor (GRPR) and integrin αvβ3 bispecific radiotracers for imaging prostate cancer." (PMID 36770755, 2023). "[99mTc]Tc-maSSS-PEG2-RM26 demonstrated strong affinity for GRPR along with favorable biodistribution and dosimetry, showing promise for SPECT imaging of GRPR-positive prostate cancer." (PMID 37175001, 2023). "Radiolabeled gastrin-releasing peptide receptor (GRPR) antagonists have shown great promise for the theranostics of prostate cancer; however, their suboptimal metabolic stability leaves room for improvements." (PMID 37509170, 2023). "Various GRPR antagonists have been developed and evaluated in preclinical and early-phase clinical studies, showing great promise for imaging of GRPR-expressing prostate cancer." (PMID 37175001, 2023). "Further, GRPR expression in prostate cancer is higher in the earlier stages of the disease and is androgen-dependent." (PMID 37509170, 2023). "Several GRPR radioligands have been developed and evaluated in preclinical and early-phase clinical studies in prostate cancer patients, demonstrating great potential and safety for theranostic application." (PMID 37509170, 2023). "In a following study in a small number of therapy-naïve prostate cancer patients [68Ga]Ga-SB3 showed high diagnostic sensitivity and excellent correlation with GRPR-status in primary cancer lesions." (PMID 37242457, 2023). "In the GRPR+ prostate cancer PC3 cell line, the cytotoxic activity of the designed AuNP-BBN-Pt nanoparticles is strongly influenced by the presence of the PEGylated linker." (PMID 36593794, 2023). "In the last decades, several GRPR-targeting molecules have been evaluated both at preclinical and clinical level, however, most of the studies have been focused on prostate cancer (PC)." (PMID 38020178, 2023). "Numerous GRPR radioantagonists have been developed and evaluated thus far, showing great potential in prostate cancer management." (PMID 37509170, 2023). "Most of the studies have been focused on the development of GRPR radiopeptides for prostate cancer (PC) theranostics, also because of their important role in tumors with low Prostate Specific Membrane Antigen (PSMA) expression." (PMID 38020178, 2023).